HNRNPA0 (heterogeneous nuclear ribonucleoprotein A0)
Description:
mRNA-binding component of ribonucleosomes. Specifically binds AU-rich element (ARE)-containing mRNAs. Involved in post-transcriptional regulation of cytokines mRNAs.
Synonyms: HNRPA0
Tractability: PROTAC: UniProt records ubiquitination sites on it; ubiquitination databases record sites on it; its protein half-life has been measured.
Gene: Protein-coding gene on chromosome 5 (137,745,651 to 137,754,363, reverse strand). Ensembl gene ENSG00000177733.
Subcellular location: Nucleus
Subcellular location (Human Protein Atlas): Nucleoplasm
Pathways (Reactome):
Disease: Dengue Virus-Host Interactions
Gene Ontology:
Molecular function: mRNA 3'-UTR AU-rich region binding; protein binding; protein kinase binding; RNA binding; nucleic acid binding
Biological process: 3'-UTR-mediated mRNA stabilization; inflammatory response; mRNA processing; response to lipopolysaccharide
Cellular component: nucleoplasm; nucleus; synapse
Genetic constraint (gnomAD): Loss-of-function variants: 0 observed, 2 expected, observed/expected ratio (o/e) 0, 90% interval 0 to 1.35. That is too few expected variants to judge how well the gene tolerates losing a copy. Missense variants: 252 observed, 457.3 expected, observed/expected ratio (o/e) 0.55, 90% interval 0.5 to 0.61. Synonymous variants: 243 observed, 207.03 expected, observed/expected ratio (o/e) 1.17, 90% interval 1.06 to 1.3.
Homologues: Orthologues: chimpanzee HNRNPA0 (100% identical), guinea pig HNRNPA0 (98% identical), rat Hnrnpa0 (94% identical), mouse Hnrnpa0 (93% identical), tropical clawed frog hnrnpa0 (70% identical). Paralogues in human: HNRNPA3 (43% identical), HNRNPA1 (42% identical), HNRNPA1L3 (42% identical), HNRNPA1L2 (41% identical), HNRNPA2B1 (39% identical), MSI2 (34% identical), MSI1 (33% identical), DAZAP1 (32% identical), HNRNPD (30% identical), HNRNPDL (30% identical), HNRNPAB (28% identical), RBMX (25% identical), and 24 more.
Diseases named in the same sentence as HNRNPA0 in open-access papers:
HNRNPA0 is named in the same sentence as 25 diseases in open-access papers, as found by Europe PMC text mining. Sharing a sentence is not in itself a finding about the gene and the disease. The quoted sentences say what the papers report.
esophageal cancer (4 papers, 2020 to 2024). A primary or metastatic malignant neoplasm involving the esophagus. "LncRNA miR205HG interacts with HNRNPA0 mRNA and then inhibits the migration and invasion of esophageal carcinoma cells." (PMID 38347041, 2024). "However, the translation process and oncogenic effects of hnRNPA0 could be hindered by lncRNA miR205HG in esophageal carcinoma (ESCA), in which hnRNPA0 was highly expressed." (PMID 35879279, 2022). "The knockdown of hnRNPA0 also exerted anti-tumor effects in other cancer cell lines, including gastric cancer MKN45 cells, pancreatic cancer SUIT-2 cells and PANC-1 cells, and esophageal cancer OE33 cells." (PMID 32303675, 2020).
colorectal cancer (3 papers, 2020 to 2022). A primary or metastatic malignant neoplasm that affects the colon or rectum. "The downregulation assay of 20 representative hnRNPs, a major family of RNA-binding proteins, in colorectal cancer cells revealed that hnRNPA0 is a strong regulator of cancer cell growth." (PMID 32303675, 2020). "Flow cytometry and Western blotting analyses revealed that hnRNPA0 inhibited the apoptosis through the maintenance of G2/M phase promotion in colorectal cancer cells." (PMID 32303675, 2020).
lung carcinoma (3 papers, 2020 to 2025). "Notably, HNRNPA0 stabilizes Gadd45α and p27(Kip1) mRNAs upon DNA damage, contributing to chemotherapy resistance in lung cancer and to hematopoietic lineage fate decisions in murine models through post-transcriptional regulation of ARE-containing transcripts." (PMID 41200172, 2025). "The upregulation of HNRNPA0 and PSCA is also associated with cisplatin resistance in lung cancer." (PMID 33170151, 2020).
Amoebiasis (1 paper, 2025). "GSEA results suggested that HNRNPA0 was primarily involved in pathways like Amoebiasis, Ascorbate and aldarate metabolism." (PMID 41200172, 2025).
breast carcinoma (1 paper, 2020). "Interestingly, protein abundance of HPRT1, HNRNPA0, IFIT3, CTNND1 and EIF4A3 predicted poor overall survival in breast cancer patients, however, PPM1A association was non-significant." (PMID 32532008, 2020).
cognitive decline (1 paper, 2019). "We present here evidence to suggest that expression levels of HNRNPM, HNRNPA0 and AKAP17A genes may be associated with cognitive decline, whilst AKAP17A levels may be associated with decline in physical performance in a human population." (PMID 31292793, 2019).
gastric cancer (1 paper, 2020). A primary or metastatic malignant neoplasm involving the stomach. "The tumor promotive function of hnRNPA0 was confirmed in gastrointestinal cancer cells, including pancreatic, esophageal, and gastric cancer cells, but not in non-cancerous cells." (PMID 32303675, 2020).
myeloid neoplasm (1 paper, 2022). Proliferation of myeloid cells originating from a primitive stem cell. "Studies have shown that hnRNPA0 is located within the commonly deleted segment of 5q31.2 in myeloid neoplasms (MNs) with a del(5q)." (PMID 35879279, 2022). "Meanwhile, a decreased dose of hnRNPA0 in therapy-related myeloid neoplasms (t-MNs) patients may contribute to leukemogenesis." (PMID 35879279, 2022).
tauopathy (1 paper, 2018). Neurodegenerative disorders involving deposition of abnormal tau protein isoforms (tau proteins) in neurons and glial cells in the brain. "Interestingly, the third group of proteins whose association with tau increased in the 2.5 m mice was nucleotide binding proteins; these include RBPs such as EWSR1, TAF15 and HNRNPA0, which we previously reported to co-localize with tau pathology in the rTg4510 model of tauopathy." (PMID 30068389, 2018).
cancer (13 papers, 2015 to 2025). A tumor composed of atypical neoplastic, often pleomorphic cells that invade other tissues. "Recently, the abnormality of hnRNPA0 has gradually proved to be firmly associated with cancer development." (PMID 35879279, 2022). "Interestingly, hnRNPA0 mutation has also been found to be related to increased cancer incidence in a large family cursed with strong familial susceptibility to cancers." (PMID 35879279, 2022). "A HNRNPA0 mutation can affect the expression pattern of phosphatidylinositol-3 kinase and extracellular signal-regulated kinase/mitogen-activated protein kinase signaling pathway, and increase the risk of cancer." (PMID 36147491, 2022). "It was reported that cancer-specific phosphorylated hnRNPA0 facilitated chromosomal alignment in mitosis and promoted CRC cell progression through RAB3GAP1-ZWINT1 cascade." (PMID 35879279, 2022). "Moreover, hnRNPA0 was also regarded as a strong promoter for various cancers such as hereditary colorectal cancer (CRC), metastatic clear cell renal cell carcinoma (ccRCC) and endometrial cancer (EC)." (PMID 35879279, 2022). "Actually, the study on hnRNPA0 in cancer is still in its infancy, and its specific mechanisms and molecular regulatory networks in the cancer process remain unclear, thus there is still a long way to go to reach the final clinical transformation." (PMID 35879279, 2022). "Other genes like HNRNPA0, DCAF7, and TRIM52 functioned in diverse ways including abnormal changes in alternative splicing or activation of canonical signal pathways in relation with cancer progression." (PMID 33134164, 2020).
tumor (6 papers, 2020 to 2024). "Importantly, these findings were phenocopied in nu/nu mouse experiments whereby the stable knockdown of hnRNPA0 in HT‐29.shLIMp27 xenografts rescued the effects of LIMp27 knockdown, reversing decreases in tumor growth and increases in the expression of p27 mRNA." (PMID 36638271, 2023). "Genes related to oxidative phosphorylation and those related with chemoresistance and poor prognosis such as HNRNPA0, HDAC1, LDHB, AREG, and PSCA were upregulated in subgroups of brain metastasis-derived tumor cells in chemotherapy treated patients." (PMID 33170151, 2020).
neurodegenerative disease (1 paper, 2025). A disorder of the central nervous system characterized by gradual and progressive loss of neural tissue and neurologic function. "In line with recent findings in neurodegenerative diseases where HNRNPA0 forms insoluble aggregates with tau protein, its dysregulation may also reflect broader RNA-processing disturbances under chronic inflammatory conditions." (PMID 41200172, 2025).
HNRNPA0 also shares sentences with these, for which no sentence is quoted: cervical cancer (1 paper); colon cancer (1); colorectal tumoral (1); COVID-19 (1); dengue (1); esophageal adenocarcinoma (1); infection (1); lung squamous cell carcinoma (1); lymph node metastases (1); melanoma (1); metastatic cancer (1); osteosarcoma (1); pancreatic cancer (1).